NEIL2 (nei like DNA glycosylase 2)
Diseases named in the same sentence as NEIL2 in open-access papers (continued):
Sharing a sentence is not in itself a finding about the gene and the disease.
rectal adenomas (1 paper, 2013). "Significant associations were also observed for two unlinked tagSNPs in the NEIL2 gene and rectal adenoma risk." (PMID 23951112, 2013). "Significant associations were also observed between SNPs in the NEIL2 gene and rectal adenoma risk." (PMID 23951112, 2013). "Two NEIL2 SNPs, rs11785481 and rs3757949, were associated with risk for rectal adenomas." (PMID 23951112, 2013).
rectal cancer (1 paper, 2020). A primary or metastatic malignant neoplasm that affects the rectum. "Another study reported that genetic mutations in the coding region of the NEIL2 gene correlated with the risk of rectal cancer." (PMID 32626527, 2020).
cancer (18 papers, 2006 to 2025). A tumor composed of atypical neoplastic, often pleomorphic cells that invade other tissues. "Previous work has shown that the reduced expression of the NEIL2 protein is associated with the progression of several types of cancer, including CRC." (PMID 32872214, 2020). "In this report, we have tried to gain molecular insight into a single nucleotide polymorphism (SNP) in the NEIL2 gene previously identified as “cancer risk modifier” for BRCA2 mutation carriers." (PMID 29383107, 2017). "In particular, two Single Nucleotide Polymorphisms (SNPs) in the OGG1 and NEIL2 genes were identified as cancer risk modifiers for BRCA1 and BRCA2 mutation carriers, respectively." (PMID 29383107, 2017). "Future genome-wide analyses of cancers derived from individuals with germline NEIL1 or NEIL2 mutations should clarify the role of NEIL1 and NEIL2 in the prevention of mutations." (PMID 27042257, 2016). "Numerous studies have indicated that any alteration in NEIL1 expression can lead to the deregulation of cell death and carcinogenesis and reported that, in diverse cancers, the abnormal expressions of NEIL2 were widely associated with the somatic mutation load." (PMID 37298600, 2023). "Besides METTL1 and NEIL2, several of the differentially methylated genes identified by analysis of associated promoter methylation, or of all genes, have roles in cancer biology." (PMID 33266012, 2020). "Our results suggest that an excessive production of NEIL2 enzyme, associated with the SNP, may have a deleterious effect modifying cancer risk susceptibility in BRCA2 mutation carriers." (PMID 29383107, 2017). "Human cells containing such NEIL1 or NEIL2 mutations are considered to have a reduced capacity to repair mutagenic bases; thus, similar to cancers with a reduced NEIL1 or NEIL2 expression levels, a higher incidence of mutation is likely to occur in the cells, leading to cancer susceptibility." (PMID 27042257, 2016). "To identify the mechanism underlying the reduction in NEIL1 and NEIL2 expression in cancer, we investigated whether these genes were epigenetically silenced in cancer using DNA methylation data from the TCGA database." (PMID 27042257, 2016). "A recent analysis of copy number variation using the data from COSMIC and TCGA databases revealed that NEIL2's level is generally low in most cancers." (PMID 33932404, 2021). "The reduced expression of NEIL1, NEIL2, and elevated expression of NEIL3 is involved in the progression of several types of cancer as a consequence of somatic mutation load." (PMID 32872214, 2020). "Using a TCGA-based analysis, associations between abnormal NEIL1, NEIL2, or NEIL3 expressions and the somatic mutation load were apparently demonstrated in various cancer types for the first time." (PMID 27042257, 2016). "The total mutation loads were significantly higher in the group of cancers with the lower NEIL1 and NEIL2 expression levels in 4 of the 13 (30.8%) cancer types and 2 of the 13 (15.4%) cancer types, respectively." (PMID 27042257, 2016). "Then, the median mutation loads for each cancer type and the median NEIL1, NEIL2, and NEIL3 expression values normalized to the expression value of the constitutive housekeeping gene YWHAZ (ENSG00000164924) were analyzed to identify correlations." (PMID 27042257, 2016). "The levels of NEIL1 and NEIL2 mRNA expression in tumor tissue, compared with normal tissue, were significantly reduced in 6 of the 13 (46.2%) cancer types and 4 of the 13 (30.8%) cancer types, respectively." (PMID 27042257, 2016). "We found, for the first time, that the abnormal expressions of NEIL1, NEIL2, and NEIL3 are associated with somatic mutation loads in diverse cancers." (PMID 27042257, 2016). "NEIL2 protein levels were extremely low in 50% of cancer tissues examined and higher than normal in only 8% cancer cases." (PMID 24595271, 2014).
cancer (continued). "NEIL2 may act as an important marker for predicting radiosensitivity in patients with cancer and is related to overall survival." (PMID 40761744, 2025). "The decreased level or loss of activity of NEIL2 and, to a lesser extent, NEIL1, is a risk factor for the progression of cancers such as lung cancer and squamous cell carcinoma in the oral cavity, and poor survival in patients with estrogen-receptor-positive breast cancer." (PMID 32872214, 2020). "We next investigated whether the abnormal expressions of NEIL1, NEIL2, and NEIL3 were associated with the mutation load in each cancer type." (PMID 27042257, 2016). "Next, we attempted to investigate the expression statuses of NEIL1, NEIL2, and NEIL3 in each cancer type and to determine whether their abnormal expressions were associated with the mutation load of each cancer." (PMID 27042257, 2016). "In this report, we describe the noncanonical role of NEIL2 as a repressor of NF-κB that has the potential to mitigate complications of hyperinflammation associated with various human pathologies including chronic inflammatory diseases and cancer." (PMID 33932404, 2021). "Using data for 13 cancer types from the TCGA database, we revealed that the median somatic total and SNP-type mutation loads exhibited significant inverse correlations with the median NEIL1 and NEIL2 expression levels and a significant positive correlation with the median NEIL3 expression level." (PMID 27042257, 2016). "In conclusion, our study indicates that the abnormal expressions of NEIL1, NEIL2, and NEIL3 are likely to be involved in mutagenesis in human cancer." (PMID 27042257, 2016). "We also showed that a subset of human cancers exhibited reduced NEIL1 and NEIL2 expression levels and an elevated NEIL3 expression level, and these abnormal expressions of NEIL1, NEIL2, and NEIL3 were associated with the mutation load in cancer." (PMID 27042257, 2016). "In this study, the 0.5-fold, 0.5-fold, and 2.5-fold values of the median expression value in noncancerous tissue samples of each organ were used as cut-off values to dichotomize the NEIL1, NEIL2, and NEIL3 expression values in the cancer cases, respectively." (PMID 27042257, 2016). "A subset of the cancer types exhibited reduced NEIL1 and NEIL2 expressions and elevated NEIL3 expression, and such abnormal expressions of NEIL1, NEIL2, and NEIL3 were also significantly associated with the mutation loads in cancer." (PMID 27042257, 2016). "However, some mechanistic aspects have not fully been clarified yet, e.g., NEIL1, NEIL2 and NEIL3 triple-knockout mice were not prone to cancer and do not have increased mutational frequency produced by defective BER." (PMID 32252452, 2020). "The effects of abnormalities in the DNA glycosylases NEIL1, NEIL2, and NEIL3 on human cancer have not been fully elucidated." (PMID 27042257, 2016).
tumor (11 papers, 2016 to 2025). "Some of studies were found that the mutation of NEIL2 gene was associated with tumor development and progression." (PMID 32626527, 2020). "The ability to repair DNA damage caused by platinum-based chemotherapy was enhanced by increased intracellular NEIL2 protein, which leads to tumor resistance to platinum-based chemotherapy." (PMID 32626527, 2020). "To validate this relationship between DNA repair genes and potential oncogenic or tumor suppressive roles, we utilized the TCGA database to analyze NEIL2 and RRM2B, the repair genes with the highest frequency of CNV loss and gain, respectively." (PMID 27004405, 2016). "Although Neil2-null (Neil2−/−) mice are viable and do not show spontaneous tumor development, their susceptibility to inflammatory stimuli prompted us to explore the mechanistic basis of NEIL2's role in innate immunity." (PMID 33932404, 2021). "mRNA and protein expression of NEIL2 was measured in 92 freshly-obtained CSCC tumor tissues." (PMID 32198476, 2020). "NEIL2 is located at 8p23.1, a region that has been linked to tumorigenesis and patient prognosis; CCNE1 is located at 19q12, and its amplification has been shown to promote tumor cell proliferation." (PMID 28603669, 2017). "In addition, we have observed that NEIL2 gene is frequently upregulated in several tumor types, and more importantly that NEIL2 mRNA upregulation or copy number amplification has prognostic value for some of those tumors." (PMID 29383107, 2017). "Therefore, NEIL2 may be a potential drug target for tumor chemosensitivity, which provides a new prospect for chemotherapy in patients and opens a new field for improving the prognosis of patients with NSCLC." (PMID 32626527, 2020). "Besides, we also observed that MSH4, NBN, NEIL2, OGG1 and XRCC2 were downregulated in both HPV-positive tumor cell lines when compared to the HPV-negative one." (PMID 30674977, 2019).
infection (5 papers, 2020 to 2025). The state of being infected such as from the introduction of a foreign agent such as serum, vaccine, antigenic substance or organism. "We have made similar observations in SARS-CoV-2 infected patients, the severity of the infection and the rate of survival are highly correlated with NEIL2 deficiency." (PMID 37423306, 2023). "Hence, this seminal observation of higher DSBs in the Neil2 KO mice EDMs following infection with Fn might open up a new direction to study how NEIL2 deficiency can trigger DSB formation." (PMID 32872214, 2020). "H. pylori infection reduces NEIL2 expression in a manner dependent on the duration and intensity of infection." (PMID 40033009, 2025). "NEIL2 counteracts the action of NF-κB on the IFN-β promoter shortly after infection, thus restraining the amplification of gene expression by IFNs." (PMID 40033009, 2025). "Our results show that NEIL2 antagonizes nuclear factor κB (NF-κB) acting on the IFN-β promoter early after infection, thus limiting gene expression amplified by type I IFNs." (PMID 37423306, 2023). "Comparative expression profiling of uninfected vs. SARS-CoV-2 infected lung epithelial cells (Calu3, GSE147507) also displayed a significant decrease in NEIL2 transcript levels post infection." (PMID 38071370, 2023). "When suffering from an infection, Nei-like DNA glycosylase 2 (NEIL2), an oxidized base-specific DNA glycosylase, significantly relieves inflammation response and DNA damage." (PMID 35800370, 2022). "Next, we assessed the expression level of BER proteins in the EDM cell lysates and found that Fn infection suppressed the expression of the NEIL2 protein." (PMID 32872214, 2020). "As we have shown that NEIL2 prevents DNA damage accumulation following infection with H. pylori, we therefore examined the level of oxidized DNA bases in WT vs. Neil2 KO EDMs." (PMID 32872214, 2020). "NEIL2, a mammalian DNA repair enzyme, has been reported to suppress infection induced inflammation." (PMID 38071370, 2023). "Based on the work presented here, we propose that if the levels of NEIL2 in hosts are low or the virus is able to significantly diminish the level of NEIL2 beyond a critical threshold, the virus will successfully establish infection in permissive hosts." (PMID 38071370, 2023). "(c) Our current results showed that the measurement of 8-hydroxy guanosine, LA-PCR, and the accumulation of double-strand breaks by γH2AX staining conclusively showed a higher level of DNA strand-break accumulation in WT cells after Fn infection (with a lower NEIL2 expression level)." (PMID 32872214, 2020). "Similar to human EDMs, Fn infection led to the downregulation of NEIL2 and NEIL1 transcripts." (PMID 32872214, 2020). "Therefore, NEIL2 has an important role in reducing inflammation and DNA damage following infection." (PMID 32872214, 2020). "We detected a strong association of NEIL2 with full length SARS-CoV-2 5’-UTR RNA, mimicking the in vivo post infection CoV-2 RNA-NEIL2 interactions, but not with the 5’-UTR RNA of several host genes; GAPDH, HPRT and DNA polymerase β (POLB) as controls." (PMID 38071370, 2023). "The transcript level of NEIL2 was not affected following infection with these bacteria, indicating the downregulation of NEIL2 following Fn infection is specific." (PMID 32872214, 2020). "Moreover, in the absence of NEIL2 by siRNA-mediated depletion in hSAECs and Neil2−/− mice, the expression of IFN-β is 1.5 to 2.5 folds higher than the presence of NEIL2 under mock-infection." (PMID 37423306, 2023).
NEIL2 also shares sentences with these, for which no sentence is quoted: Barrett’s esophagus (2 papers); Fanconi anemia (2); lung squamous cell carcinoma (2); neurodegenerative disease (2); adenoma (1); amyotrophic lateral sclerosis (1); asthma (1); bacterial infections (1); breast invasive carcinoma (1); cervical intraepithelial neoplasia (1); cervical squamous cell carcinoma (1); chronic obstructive pulmonary disease (1); clear cell renal cell carcinoma (1); colon adenocarcinoma (1); head and neck squamous cell carcinoma (1); Hypertension (1); inflammatory bowel disease (1); microcephaly (1); multiple sclerosis (1); non-small cell lung carcinoma (1); oropharyngeal cancer (1); Parkinson disease (1); rectal adenocarcinoma (1); respiratory syncytial virus infection (1); Stroke (1).